CYP4A22 (cytochrome P450 family 4 subfamily A member 22)
Description:
Catalyzes the omega- and (omega-1)-hydroxylation of various fatty acids such as laurate and palmitate. Shows no activity towards arachidonic acid and prostaglandin A1. Lacks functional activity in the kidney and does not contribute to renal 20-hydroxyeicosatetraenoic acid (20-HETE) biosynthesis.
Tractability: Small molecule: it belongs to a druggable protein family. Antibody: UniProt places it where antibodies can reach, with medium confidence. PROTAC: a small molecule that binds it is known.
Gene: Protein-coding gene on chromosome 1 (47,137,419 to 47,149,742, forward strand). Ensembl gene ENSG00000162365.
Subcellular location: Endoplasmic reticulum membrane; Microsome membrane
Pathways (Reactome):
Metabolism: Eicosanoids; Fatty acids; Miscellaneous substrates; Synthesis of Leukotrienes (LT) and Eoxins (EX)
Gene Ontology:
Molecular function: 16-hydroxypalmitate dehydrogenase activity; arachidonate omega-hydroxylase activity; medium-chain fatty acid omega-hydroxylase activity; alkane 1-monooxygenase activity; arachidonate monooxygenase activity; heme binding; iron ion binding; long-chain fatty acid omega-hydroxylase activity; monooxygenase activity; oxidoreductase activity, acting on paired donors, with incorporation or reduction of molecular oxygen; oxidoreductase activity, acting on paired donors, with incorporation or reduction of molecular oxygen, reduced flavin or flavoprotein as one donor, and incorporation of one atom of oxygen
Biological process: lipid hydroxylation; omega-hydroxylase P450 pathway; arachidonate metabolic process; icosanoid biosynthetic process; kidney development; lauric acid metabolic process; linoleic acid metabolic process; lipid metabolic process
Cellular component: extracellular region; endoplasmic reticulum membrane
Genetic constraint (gnomAD): Loss-of-function variants: 46 observed, 55.08 expected, observed/expected ratio (o/e) 0.84, 90% interval 0.66 to 1.07. The synonymous counts are far from expectation, so gnomAD's model fits this gene poorly and the ratio says little. Missense variants: 541 observed, 637.3 expected, observed/expected ratio (o/e) 0.85, 90% interval 0.79 to 0.91. Synonymous variants: 193 observed, 248.07 expected, observed/expected ratio (o/e) 0.78, 90% interval 0.69 to 0.88.
Homologues: Orthologues: macaque CYP4A45 (92% identical), macaque CYP4A11 (91% identical), chimpanzee CYP4A22 (81% identical), mouse Cyp4a10 (74% identical), rat Cyp4a1 (73% identical), mouse Cyp4a32 (72% identical), mouse Cyp4a31 (72% identical), rat Cyp4a3 (69% identical), mouse Cyp4a30b (67% identical), tropical clawed frog cyp4b1.5 (53% identical), tropical clawed frog cyp4b1.2 (52% identical), tropical clawed frog XB5810926 (52% identical), and 30 more. Paralogues in human: CYP4A11 (95% identical), CYP4B1 (51% identical), CYP4Z1 (49% identical), CYP4X1 (47% identical), CYP4F3 (44% identical), CYP4F2 (44% identical), CYP4F11 (44% identical), CYP4F8 (43% identical), CYP4F12 (42% identical), CYP4F22 (41% identical), CYP4V2 (31% identical), CYP19A1 (20% identical).
Diseases named in the same sentence as CYP4A22 in open-access papers:
CYP4A22 is named in the same sentence as 14 diseases in open-access papers, as found by Europe PMC text mining. Sharing a sentence is not in itself a finding about the gene and the disease. The quoted sentences say what the papers report.
Cirrhosis (2 papers, 2021 to 2024). A chronic disorder of the liver in which liver tissue becomes scarred and is partially replaced by regenerative nodules and fibrotic tissue resulting in loss of liver function. "We also explored CYP4A11 and CYP4A22 expression in the liver of patients with cirrhosis using a recently published and publicly available data set." (PMID 34423788, 2021). "We found that both CYP4A11 and CYP4A22 were highly expressed specifically in hepatocytes compared with nonhepatic parenchymal cells, and that levels increased in patients with cirrhosis compared with healthy controls." (PMID 34423788, 2021). "In liver samples of cirrhosis, CYP4A22 increases while CYP4A11 and CYP4F2 decrease." (PMID 39959811, 2024).
essential hypertension (2 papers, 2016 to 2024). Hypertension that presents without an identifiable cause. "In particular, SNP rs4926600 on chromosome 1 is within gene CYP4A22, which was previously reported to be associated with essential hypertension." (PMID 27980654, 2016). "In overall and some stratified analyses (male, age ≤ 60 years or CHD patients complicated with hypertension), CYP4A22-rs12564525 (overall, OR = 0.83, p-value is 0.042) and CYP4A22-rs2056900 (overall, OR = 1.22, p-value is 0.032) were associated with the risk of CHD." (PMID 38438909, 2024).
alcoholic liver diseases (1 paper, 2021). A disorder caused by damage to the liver parenchyma due to alcohol consumption. "To determine if CYP4A is involved in ALD pathogenesis in humans, we detected the mRNA expression of CYP4A11 (homolog of murine Cyp4a14) and CYP4A22 (homolog of murine Cyp4a10) in the liver of patients with alcoholic liver disease." (PMID 34423788, 2021).
coronary heart disease (1 paper, 2024). "In summary, the results of this study suggested that CYP4A22-rs12564525, -rs2056900, -rs4926581 were associated with coronary heart disease susceptibility." (PMID 38438909, 2024).
gastric cancer (1 paper, 2024). A primary or metastatic malignant neoplasm involving the stomach. "The expression of CYP4A22 and MAP17 was moderately upregulated in gastric cancer cell lines compared to that in normal cells." (PMID 38586313, 2024).
hepatocellular carcinoma (1 paper, 2023). A malignant tumor that arises from hepatocytes. "DisGenNET lists liver carcinoma as a disease linked to CYP4A22, and links to PubMed ID 30069903, which indicates that higher CYP4A22 expression in hepatocellular carcinoma correlates with better disease prognosis." (PMID 37296383, 2023).
hypospadias (1 paper, 2020). Hypospadias is the displacement of the urethral meatus on the ventrum of the penis. "We identified a significant causal effect of methylation at cg04714159 on hypospadias, as well as potential causal effects of multiple members of the cytochrome P450 family of enzymes in this region (CYP4A11, CYP4A22, CYP4B1, CYP4X1, CYP4Z2P)." (PMID 32728162, 2020).
liver cirrhosis (1 paper, 2024). "Unlike CYP4A11 mRNA and P4504A11 protein that dramatically decrease in liver cirrhosis patients, CYP4A22 mRNA and P4504A22 protein levels increase." (PMID 39959811, 2024).
rickets (1 paper, 2024). Bone softening and weakening usually caused by deficiency or impaired metabolism of vitamin D. Deficiency of calcium, magnesium, or phosphorus may also cause rickets. "Recently, the CYP4A22 gene has been implicated in vitamin D-dependent rickets through its ability to function as a 25-hydroxylase for vitamin D3." (PMID 39959811, 2024).
steatosis (1 paper, 2024). Increased lipid within the cytoplasm of cells. "Our data indicate that both CYP4A11, CYP4A22, and CYP4F2 mRNA levels increase in steatosis while both CYP4A11 and CYP4A22 increase in steatohepatitis." (PMID 39959811, 2024).
CYP4A22 also shares sentences with these, for which no sentence is quoted: cancer (1 paper); glioblastoma (1); Hypertension (1); tumor (1).